GRIN2A (glutamate ionotropic receptor NMDA type subunit 2A)
Description:
Component of N-methyl-D-aspartate (NMDA) receptors (NMDARs) that function as heterotetrameric, ligand-gated cation channels with high calcium permeability and voltage-dependent block by Mg(2+). NMDARs participate in synaptic plasticity for learning and memory formation by contributing to the slow phase of excitatory postsynaptic current, long-term synaptic potentiation, and learning (By similarity). Channel activation requires binding of the neurotransmitter L-glutamate to the GluN2 subunit, glycine or D-serine binding to the GluN1 subunit, plus membrane depolarization to eliminate channel inhibition by Mg(2+). NMDARs mediate simultaneously the potassium efflux and the influx of calcium and sodium (By similarity). Each GluN2 subunit confers differential attributes to channel properties, including activation, deactivation and desensitization kinetics, pH sensitivity, Ca2(+) permeability, and binding to allosteric modulators. Participates in the synaptic plasticity regulation through activation by the L-glutamate releaseed by BEST1, into the synaptic cleft, upon F2R/PAR-1 activation in astrocyte (By similarity).
Synonyms: GluN2A; NMDAR2A; NR2A; EPND; FESD; LKS
Tractability: Small molecule: an approved drug acts on it; a structure with a bound ligand is known; a high-quality ligand is known; it belongs to a druggable protein family. Antibody: UniProt places it where antibodies can reach, with high confidence; its Gene Ontology location is reachable by antibodies, with high confidence; UniProt predicts a signal peptide or a membrane-spanning region. PROTAC: ubiquitination databases record sites on it; a small molecule that binds it is known. Other modalities: a drug acting on it is in phase 2 or 3 trials.
Target class: Ion channel; Ionotropic glutamate receptor; Ligand-gated ion channel; NMDA receptor
Chemical probes: JNJ-78911118 (high quality), TP-050 (high quality)
Safety:
Unwanted effects reported when the protein is acted on. In parentheses: how it was acted on, where the effect was seen, and who reports it.
ataxia (inhibition, acute dosing; central nervous system, cardiovascular; source: Lynch et al. (2017))
convulsions (activation, acute dosing; central nervous system, cardiovascular; source: Lynch et al. (2017))
decreased convulsions (inhibition, acute dosing; central nervous system, cardiovascular; source: Lynch et al. (2017))
decreased memory (inhibition, acute dosing; central nervous system, cardiovascular; source: Lynch et al. (2017))
decreased pain (inhibition, acute dosing; central nervous system, cardiovascular; source: Lynch et al. (2017))
dizziness (inhibition, acute dosing; central nervous system, cardiovascular; source: Lynch et al. (2017))
drug abuse/dependence (inhibition, acute dosing; central nervous system, cardiovascular; source: Lynch et al. (2017))
impaired social interactions (inhibition, chronic dosing; central nervous system, cardiovascular; source: Lynch et al. (2017))
increased blood pressure (inhibition, acute dosing and activation, acute dosing; central nervous system, cardiovascular; source: Lynch et al. (2017))
increased heart rate (inhibition, acute dosing; central nervous system, cardiovascular; source: Lynch et al. (2017))
increased locomotor activity (inhibition, acute dosing; central nervous system, cardiovascular; source: Lynch et al. (2017))
increased then decreased heart rate (activation, acute dosing; central nervous system, cardiovascular; source: Lynch et al. (2017))
neurodegeneration (inhibition, chronic dosing; central nervous system, cardiovascular; source: Lynch et al. (2017))
neurotoxicity (inhibition, acute dosing; central nervous system, cardiovascular; source: Lynch et al. (2017))
pain (activation, acute dosing; central nervous system, cardiovascular; source: Lynch et al. (2017))
psychosis (inhibition, chronic or acute dosing; central nervous system, cardiovascular; source: Lynch et al. (2017))
stereotypy (inhibition, chronic dosing; central nervous system, cardiovascular; source: Lynch et al. (2017))
Gene: Protein-coding gene on chromosome 16 (9,753,404 to 10,183,337, reverse strand). Ensembl gene ENSG00000183454.
Subcellular location: Cell projection, dendritic spine; Cell membrane; Synapse; Postsynaptic cell membrane; Cytoplasmic vesicle membrane
Subcellular location (Human Protein Atlas): Endoplasmic reticulum; Vesicles
Pathways (Reactome):
Neuronal System: Assembly and cell surface presentation of NMDA receptors; Long-term potentiation; Negative regulation of NMDA receptor-mediated neuronal transmission; Neurexins and neuroligins; Synaptic adhesion-like molecules; Unblocking of NMDA receptors, glutamate binding and activation
Gene Ontology:
Molecular function: glutamate-gated calcium ion channel activity; NMDA glutamate receptor activity; protein binding; amyloid-beta binding; transmitter-gated monoatomic ion channel activity involved in regulation of postsynaptic membrane potential; zinc ion binding; calcium channel activity; ligand-gated monoatomic ion channel activity; monoatomic cation channel activity; monoatomic ion channel activity; signaling receptor activity
Biological process: calcium ion transmembrane import into cytosol; calcium ion transmembrane transport; cellular response to amyloid-beta; monoatomic cation transmembrane transport; response to ethanol; sodium ion transmembrane transport; brain development; chemical synaptic transmission; excitatory chemical synaptic transmission; excitatory postsynaptic potential; glutamate receptor signaling pathway; ionotropic glutamate receptor signaling pathway; learning or memory; long-term synaptic potentiation; positive regulation of excitatory postsynaptic potential; positive regulation of synaptic transmission, glutamatergic; regulation of monoatomic cation transmembrane transport; regulation of neuronal synaptic plasticity; regulation of synaptic plasticity; synaptic transmission, glutamatergic; calcium-mediated signaling; modulation of chemical synaptic transmission; monoatomic ion transport
Cellular component: NMDA selective glutamate receptor complex; plasma membrane; cell surface; cytoplasmic vesicle membrane; endoplasmic reticulum membrane; postsynaptic density; postsynaptic density membrane; postsynaptic membrane; synapse; synaptic membrane; dendritic spine; endoplasmic reticulum; glutamatergic synapse; membrane; neuron projection; postsynapse; presynaptic membrane; synaptic vesicle
Genetic constraint (gnomAD): Loss-of-function variants: 20 observed, 108.31 expected, observed/expected ratio (o/e) 0.18, 90% interval 0.13 to 0.27. The upper end of that interval is the gene's LOEUF score, 0.27, which puts it in group 1 of 6, group 1 being the genes least tolerant of losing a copy. Missense variants: 1,475 observed, 1,922 expected, observed/expected ratio (o/e) 0.77, 90% interval 0.73 to 0.8. Synonymous variants: 812 observed, 761.62 expected, observed/expected ratio (o/e) 1.07, 90% interval 1.01 to 1.13.
Gene-disease validity (ClinGen):
ClinGen rates the evidence that GRIN2A causes each of these diseases.
complex neurodevelopmental disorder (autosomal dominant): Definitive. A disorder that involves more than one phenotype associated with the central nervous system, including but not limited to intellectual disability, autism, and seizures (epilepsy).
Cancer hallmarks: invasion and metastasis (suppresses); proliferative signalling (promotes); suppression of growth (promotes)
Homologues: Orthologues: macaque GRIN2A (98% identical), guinea pig GRIN2A (95% identical), mouse Grin2a (95% identical), rat Grin2a (95% identical), pig GRIN2A (95% identical), dog GRIN2A (95% identical), chimpanzee GRIN2A (92% identical), tropical clawed frog grin2a (73% identical), zebrafish grin2aa (67% identical), rabbit GRIN2A (66% identical), zebrafish grin2ab (57% identical), Drosophila melanogaster Nmdar2 (19% identical), and 31 more. Paralogues in human: GRIN2B (52% identical), GRIN2C (37% identical), GRIN2D (36% identical), GRIN3B (17% identical), GRIN3A (17% identical), GRIN1 (14% identical), GRIK1 (14% identical), GRIK3 (14% identical), GRIK2 (14% identical), GRIK5 (14% identical), GRIA3 (13% identical), GRIA4 (13% identical), and 5 more.
Diseases named in the same sentence as GRIN2A in open-access papers:
GRIN2A is named in the same sentence as 181 diseases in open-access papers, as found by Europe PMC text mining. Sharing a sentence is not in itself a finding about the gene and the disease. The quoted sentences say what the papers report.
schizophrenia (136 papers, 2009 to 2026). A major psychotic disorder characterized by abnormalities in the perception or expression of reality. "In parallel, genetic investigations, including exome sequencing and genome-wide association studies, have pinpointed the GRIN2A gene, encoding the GluN2A subunit, as a significant risk factor for schizophrenia." (PMID 40931040, 2026). "Recent analyses have identified GRIN2A as a gene associated with susceptibility to schizophrenia, and the GluN2A subunit is also suggested to mediate the antidepressant effects of ketamine." (PMID 40931040, 2026). "It was recently identified that rare variants in GRIN2A encoding the GluN2A subunit of the N-methyl-D-aspartate receptor (NMDAR) confer a substantial risk for schizophrenia." (PMID 41087560, 2026). "A recent exome sequencing study identified rare coding variants in 10 genes conferring substantial risk for schizophrenia, including protein-truncating null variants in GRIN2A (GRIN2Anull; overall p-value 7×10−7, Odds Ratio = 24.1)." (PMID 41087560, 2026). "We identified null variants in GRIN2A (GRIN2Anull) to be significantly associated with a broad spectrum of mental disorders including schizophrenia compared to a longitudinal population cohort (FinRegistry) as well as missense variants (GRIN2Amissense)." (PMID 41087560, 2026). "A recent study even reported evidence that EEG phenotypes of Grin2a mutant mice show a variety of abnormal features that overlap considerably with human schizophrenia patients, reflecting systems-level changes caused by Grin2a deficiency." (PMID 41087560, 2026). "Another gene encoding a glutamate receptor subunit, GRIN2A, has been associated with schizophrenia through fine-mapping and functional genomic analyses." (PMID 40943654, 2025). "High-risk variants for schizophrenia were identified in the PTVs of Grin2A, Herc1, and Trio through exome analysis." (PMID 39774335, 2025). "Fifth, the clinical presentation of only a single case of schizophrenia in a carrier of a rare loss-of-function variant in GRIN2A is examined." (PMID 40701976, 2025). "Two genes are surely associated with schizophrenia through common and rare variants: GRIN2A and SP48)." (PMID 40969821, 2025). "In humans, heterozygous loss of function variants in the gene encoding it (GRIN2A) increase the risk of epilepsy, intellectual disability and schizophrenia." (PMID 40226380, 2025). "Mice heterozygous for a LoF mutation of Grin2a model several aspects of schizophrenia and show large-scale transcriptomic changes across the brain." (PMID 41022686, 2025). "A study conducted in 2023 showed that there is an association between rs11644461 GRIN2A and the clinical phenotype of schizophrenia." (PMID 40259965, 2025). "Genetic associations further underscore this link, with GRIN2A variants conferring high schizophrenia risk (odds ratio >20 for specific mutations)." (PMID 41523331, 2025). "GRIN2A, a key glutamate system gene, is enriched in excitatory neurons and linked to several psychiatric disorders (schizophrenia, BD, MDD and cross-disorder), actively-transcribed states and DLPFC enhancers." (PMID 40253403, 2025). "We meta-analyzed large-scale brain transcriptomic data from mice harboring individual loss-of-function mutations in seven schizophrenia risk genes (Akap11, Dagla, Gria3, Grin2a, Sp4, Srrm2, Zmym2)." (PMID 41022686, 2025). "Variants in the GRIN2A gene, which encodes the GluN2A subunit, have identified it as one of the most important genes in the pathophysiology of schizophrenia and other neuropsychiatric disorders." (PMID 41465140, 2025). "GRIN2A was associated with schizophrenia through rare LoF variants in the SCHEMA study, but the clinical presentations of the schizophrenia cases harboring these variants in that study were not described." (PMID 40701976, 2025).
schizophrenia (continued). "GRIN2A is one of only two genes in the genome that have been linked to schizophrenia through both rare loss-of-function genetic variation and common genetic variation, and the other gene, SP4, encodes a transcription factor that regulates GRIN2A expression." (PMID 40701976, 2025). "As a high-risk gene for schizophrenia, GRIN2A mutations are associated with NMDA receptor hypofunction, a key feature of the pathophysiology of the disorder." (PMID 40093861, 2025). "For example, the first generation antipsychotic DRD2 antagonist Haloperidol, was also linked to schizophrenia by the off-target GRIN2A, which encodes a subunit of the glutamatergic NMDA receptor involved in synaptic plasticity and learning." (PMID 40379965, 2025). "The most common phenotypes associated with GRIN2A mutations are epilepsy/seizures, ID, and schizophrenia (SCZ)." (PMID 39596430, 2024). "Genome wide association studies in schizophrenia have identified genes encoding synaptic proteins, including GRIN2A, which encodes GluN2A." (PMID 37369776, 2024). "Recent rare variant analysis also implicates GRIN2A as one of the top genes in which loss-of-function variants are associated with schizophrenia." (PMID 37369776, 2024). "In 2011, a de novo GRIN2B pathogenic variant (c.2473T4G; p.L825V) was reported for the first time, and in the same paper, two additional de novo pathogenic GRIN2A variants were identified in two patients with sporadic schizophrenia." (PMID 39596051, 2024). "Patients with schizophrenia who have the disease-associated GRIN2A (NMDAR subunit) variant exhibit increased connectivity in striato-pallido-thalamic regions." (PMID 38979499, 2024). "GRIN2A variants exhibit truncation and missense mutations in schizophrenia, resulting in haploinsufficiency and loss of function." (PMID 39596430, 2024). "Literature associating GRIN2A common polymorphisms with schizophrenia implies that more mild changes in expression also contribute to neuropsychiatric disorder etiology." (PMID 37107537, 2023). "Taken together, these findings provide a detailed picture of the molecular landscape associated with reduction or loss of Grin2a, and a convincing convergence with the pathophysiology of schizophrenia." (PMID 37736757, 2023). "A direct relevance of these findings to schizophrenia has now emerged from findings that both rare and common variants of GRIN2A are associated with genetic risk for the disorder." (PMID 37736757, 2023). "The GRIN2A rs8057394*G allele is a relative risk factor (p = 0.019) for developing the continuous type of schizophrenia." (PMID 36980845, 2023). "The variable (GT)n polymorphism located in the promoter region of GRIN2A was shown to be related to schizophrenia." (PMID 36980845, 2023). "We found nominally significant (p < 0.05) associations with the continuous course of schizophrenia for the following polymorphisms: GRIN2A rs11644461, rs8057394; GRIN2B rs7313149." (PMID 36980845, 2023). "The neural correlates of a schizophrenia-related GRIN2A- variant were investigated by assessing resting state functional connectivity profiles in a sample of 146 patients with schizophrenia who were genotyped for this SNP." (PMID 36797233, 2023). "Among these genes, GRIN2A, which encodes the NMDAR 2A (NR2A or GluN2A) subunit, emerged as one of the most highly prioritized genes related to the pathophysiology of schizophrenia." (PMID 36797233, 2023). "The EEG phenotypes of Grin2a and Akap11 mutant mice show a variety of abnormal features that overlap considerably with human schizophrenia patients, reflecting systems-level changes caused by Grin2a and Akap11 deficiency." (PMID 36914641, 2023). "In EOP cohort participants 2 and 5, the father was the carrier of the GRIN2A variant, but the maternal side had a history of schizophrenia." (PMID 37107537, 2023). "The GRIN2A rs8057394*G allele is a relative risk factor for developing the continuous type of schizophrenia." (PMID 36980845, 2023).